NLRC3 (NLR family CARD domain containing 3)
Diseases named in the same sentence as NLRC3 in open-access papers (continued):
Sharing a sentence is not in itself a finding about the gene and the disease.
cancer (11 papers, 2015 to 2024). A tumor composed of atypical neoplastic, often pleomorphic cells that invade other tissues. "Recent studies have shown that NLRC3 is dysregulated across many cancers and implicated in their progression." (PMID 36808166, 2023). "Studies have revealed that NLRC3 expression is significantly reduced in a variety of inflammatory diseases and cancers, suggesting its potential utility as a biomarker for these conditions." (PMID 39439455, 2024). "The protein expression level of NLRC3 was further analyzed using the UALCAN (the University of Alabama at Birmingham Cancer Data Analysis Portal) omics-based web resource." (PMID 36808166, 2023). "Recently, a large body of literatures have confirmed the beneficial role of NLRC3 in cancer treatment." (PMID 36341336, 2022). "This showed that HCC patients with high NLRC3 levels in cancer tissues had a favorable survival prognosis." (PMID 35145917, 2022). "These cellular functions regulated by NLRC3 are involved in the development processes of a variety of diseases, such as infectious disease, sterile inflammatory diseases, and cancer." (PMID 36341336, 2022). "Future research will continue to investigate the functional changes that occur in NLRC3 under different pathological conditions and their impact on immune responses, with the ultimate goal of improving treatments for inflammatory diseases and cancer." (PMID 39439455, 2024). "However, CEP has been shown to reverse the decreased expression of NLRC3, which was similar to its effects in cancer." (PMID 29636680, 2018). "Furthermore, it has been revealed that mice lacking NLRC3 were predisposed to cancer due to hyperproliferation, so we identified whether addition of P. pentosaceus YC with standard diet caused harmful effect to the host." (PMID 38582865, 2024). "NLRC3 also exhibited a lower level of expression in stage 4 CRC compared to stage 1-3 CRC, suggesting its potential role in cancer progression." (PMID 26378020, 2015). "Furthermore, the extent of NLRC3 and AIM2 gene reduction was correlated with cancer progression." (PMID 26378020, 2015). "Recently NOD-like receptor family CARD domain containing 3 (NLRC3) has been identified as the upstream negative molecule in PI3K/Akt/mTOR signaling axis to inhibit the activation of PI3K, Akt and mTOR in cancer." (PMID 29881349, 2018).
bacterial infection (2 papers, 2023). "In our previous studies, NLRC3 genes in the spleen were also induced in response to bacterial infection of black rockfish and found to play a key role in a mRNA-miRNA-lncRNA regulatory network associated with the immune response." (PMID 37964222, 2023). "For example, NLRC3 genes contribute to thymic development but suppress the functions of CD4 + T cells in the spleen of mice during bacterial infection." (PMID 37964222, 2023). "In teleosts, NLRC3 genes were also found to have high expression following different bacterial infections in the intestine of channel catfish, turbot and black rockfish." (PMID 37964222, 2023). "In addition, different patterns of expression of NLRC3 genes in black rockfish following different bacterial infections has suggested the immune function of NLRC3 genes in the traditional and mucosal immune system of the Sebastidae family." (PMID 37964222, 2023). "Finally, differential expression analyses provided evidence of the immune roles of NLRC3 genes in black rockfish during bacterial infections and gene ontology analysis also indicated other functional roles." (PMID 37964222, 2023). "Finally, gene expressions of piscine NLRC3 gene repertoires were analyzed in different tissues of black rockfish following bacterial infections to infer their key roles in the immune response system of this species." (PMID 37964222, 2023). "Meanwhile, more studies were conducted on the antibacterial roles of NLRC3 genes in different teleost species, which explored and identified the significantly differential expressions (mainly in up-regulations) of piscine NLRC3 genes during bacterial infections." (PMID 37964222, 2023). "Furthermore, it has been suggested that some SsNLR isoforms (NLRC3) may express differently towards a bacterial infection (Piscirickettsia salmonis) prior to smoltification." (PMID 37834004, 2023). "Therefore, NLRC3 genes may play important roles in the immune response of black rockfish during bacterial infection, although further studies are required to determine the detail of these roles." (PMID 37964222, 2023).
infectious disease (2 papers, 2018 to 2022). A disorder directly resulting from the presence and activity of a microbial, viral, or parasitic agent in humans. "Given that CD4+ T cells showed enhanced activation phenotype under NLRC3-deficient conditions, we investigated the role of NLRC3 in the infectious disease." (PMID 30133544, 2018). "However, the ability of NLRC3 to modulate CD4+ T cell responses and the mechanisms by which NLRC3-mediated control of T cells can affect infectious disease progression remains poorly defined." (PMID 30133544, 2018). "The direct role of NLRC3 in the modulation of CD4+ T-cell responses in infectious diseases has not been studied." (PMID 30133544, 2018). "However, the direct role of NLRC3 in modulation of CD4+ T-cell responses in infectious diseases has not been studied." (PMID 30133544, 2018).
hematological disorders (1 paper, 2021). "Moreover, infected Nlrc3−/− mice showed higher viral loads in serum, spleen, and kidney than wild type C57BL/6 (WT) mice, and some of them manifested more hematological disorders and significant pathological changes within multiple organs than WT mice." (PMID 34335602, 2021).
NLRC3 also shares sentences with these, for which no sentence is quoted: macrophage activation syndrome (2 papers); albinism (1); Alzheimer disease (1); breast carcinoma (1); chronic periodontitis (1); Cirrhosis (1); enterocolitis (1); gastric cancer (1); Neonatal onset multisystem inflammatory disease (1); parasite infections (1); pulmonary hypertension (1); renal dysfunction (1); sarcoidosis (1); systemic lupus erythematosus (1); toxoplasmosis (1); viral diseases (1).